MUC16 (mucin 16, cell surface associated)
Diseases named in the same sentence as MUC16 in open-access papers (continued):
Sharing a sentence is not in itself a finding about the gene and the disease.
benign ovarian tumors (4 papers, 2018 to 2024). "We find that MUC16 and p120ctn are aberrantly overexpressed in 94 clinical OC samples compared with benign ovarian tumors (BOT)." (PMID 30795761, 2019). "To evaluate the relationship among MUC16, p120ctn and OC in patients, we analyzed the expression levels of MUC16 and p120ctn in benign ovarian tumors (BOT) and OC tissue specimens." (PMID 30795761, 2019).
cutaneous melanoma (4 papers, 2018 to 2025). A primary melanoma arising from atypical melanocytes in the skin. "Similarly, TTN was among the most frequently somatically mutated genes in both cohorts regardless of tissue site (brain, LN, or skin), and MUC16 was frequently mutated in both MDACC and Duke MBM, similar to previous reports in primary cutaneous melanomas." (PMID 40457397, 2025).
diabetes (4 papers, 2021 to 2024). "The features highlighted as predictive under these circumstances included important and widely referenced markers which we confirmed as having among the strongest association with PDAC, namely CA19-9, CEACAM5, MUC16 (CA125), THBS2 and diabetes." (PMID 36670203, 2023).
gallbladder cancer (4 papers, 2020 to 2022). "STMN1 knockdown inhibited the migration and invasion of gallbladder cancer cells induced by the MUC16 C-terminal polypeptide." (PMID 35186166, 2022). "In a recent study, positive immunohistochemical staining of MUC16 (immunoreactivity in more than 10% of the tumor cells) was observed in more than 75% of extrahepatic pancreatobiliary tumors (n = 234 cases), including 37 gallbladder cancers." (PMID 32293552, 2020). "For instance, ALDOC has been elucidated upregulated in gallbladder carcinoma (GBC) and reported to promote the growth of GBC by binding with MUC16 C-terminal." (PMID 34456184, 2021).
leukemia (4 papers, 2014 to 2022). A malignant (clonal) hematologic disorder, involving hematopoietic stem cells and characterized by the presence of primitive or atypical myeloid or lymphoid cells in the bone marrow and the blood. "Thus, we selected the TRAIL-sensitive leukemia cell line Jurkat which lacks expression of MUC16 (not shown)." (PMID 24447304, 2014).
lung fibrosis (4 papers, 2021 to 2025). "For example, muc16 (CA-125) level is considered to be a marker associated with idiopathic pulmonary fibrosis (IPF), which is the most common interstitial lung disease (ILD)." (PMID 38758220, 2024). "Investigation of the role of Msln, Muc16, and Thy1 in fibrosis and fibroblast activation across multiple organs, demonstrated that Msln−/− mice are protected from cholestatic fibrosis caused by Mdr2 deficiency, bleomycin-induced lung fibrosis, and UUO-induced kidney fibrosis." (PMID 36358290, 2022). "EMT is also implicated in pulmonary fibrosis, where TGF-β1 forms a protein complex with MUC16 CTD to activate fibrotic pathways." (PMID 40305342, 2025). "Here, we hypothesised that MUC16 C-terminal domain may collaborate to induce fibro-proliferative disorders such as pulmonary fibrosis." (PMID 34204432, 2021). "Together, these data show that MUC16 overexpression in IPF is localised to the main cells, contributing to lung fibrosis." (PMID 34204432, 2021). "Deletion of Muc16 attenuates mortality in acute model of bleomycin injury in mice, but does not protect chronically injured mice from bleomycin-induced lung fibrosis." (PMID 36358290, 2022).
triple-negative breast carcinoma (4 papers, 2021 to 2024). An invasive breast carcinoma which is negative for expression of estrogen receptor (ER), progesterone receptor (PR), and human epidermal growth factor receptor 2 (HER2). "ELAVL1 (EP: 0.0016, t-test p-value: 0.805) was found to be modulated by MUC16, which promotes triple-negative breast cancer lung metastasis." (PMID 37761960, 2023). "Furthermore, inhibiting MUC16 has been shown to suppress apoptosis in triple-negative breast cancer (TNBC) cells." (PMID 38756447, 2024).
uveal melanoma (4 papers, 2019 to 2026). A melanoma derived from melanocytes of the uveal tract. "Recent advances seen with tebentafusp in metastatic uveal melanoma and tarlatamab in small-cell lung cancer have validated the approach and driven a rapidly expanding pipeline targeting other tumor associated antigens such as STEAP1, MUC16, and PRAME among others." (PMID 41964902, 2026).
acute myeloid leukemia (3 papers, 2018 to 2023). Acute myeloid leukemia (AML) is a group of neoplasms arising from precursor cells committed to the myeloid cell-line differentiation. "(B) Overall survival of MUC4/MUC16/MUC20 high and low risk group in liver and acute myeloid leukemia (AML)." (PMID 30236127, 2018). "The observation that MUC16 is present on T cells is interesting, because recently it has been shown that Siglec-9 is overexpressed on T cells from the ascites and tumor-invading lymphocytes (TILs) of ovarian and other tumors, such as head and neck tumors or acute myeloid leukemia." (PMID 33922973, 2021).
asthma (3 papers, 2022 to 2024). "We focused on genes that correlated with one particular gene, MUC16, which encodes an IL13-induceable mucin thought to play a prominent role in asthma-associated mucus obstruction of the airway." (PMID 39294560, 2024). "The significant SNPs within loci were aligned with known asthma-susceptibility genes (e.g., ADORA1, MUC16)." (PMID 36818476, 2022). "In addition to sphingomyelins, we also observed a relationship between genes on chromosome 19p13 (e.g., MUC16), 1,2-dioleoyl-GPG, and asthma risk." (PMID 36818476, 2022). "Furthermore, the significant SNPs within two loci were aligned with known asthma-susceptibility genes (e.g., ADORA1, MUC16)." (PMID 36818476, 2022). "Furthermore, there were apparent concordances between the association peaks for two loci (i.e., chromosome 19p13 with 1,2-dioleoyl-GPG, chromosome 1q32 with sphingomyelin [d17:1/16:0, d18:1/15:0, d16:1/17:0]) and genes that are known to be related to asthma (e.g., MUC16, ADORA1)." (PMID 36818476, 2022).
bladder tumors (3 papers, 2017 to 2025). "This resulted in the identification of MUC16 as a novel biomarker for a subset of bladder tumours presenting poor prognosis." (PMID 28156048, 2017). "Although the role of MUC16 in bladder tumors is unknown, this study is the first to report MUC16 as the sialyl-Tn carrier protein." (PMID 32075174, 2020).
cholestasis (3 papers, 2017 to 2024). Impairment of the bile flow caused by obstruction within the liver, or outside the liver in the bile duct system. "These new findings suggest that Msln-Muc16-Thy-1 signaling plays an important role in the regulation of TGFβ1-TGFβRI signaling in cholestasis-activated aPFs." (PMID 34966784, 2021). "Moreover, ductular proliferation was reduced in cholestasis-injured Msln-/-Mdr2-/- mice and Muc16-/-Mdr2-/- mice, suggesting that aPF activation regulates cholangiocyte proliferation." (PMID 34966784, 2021). "MUC16 is a ligand for MSLN, and MSLN requires MUC16 for intracellular signaling to activate the MSLN/MUC16/AKT pathway, regulating cholestasis-induced proliferation of activated portal fibroblasts/myofibroblasts, but not affecting Fibrotic properties of APFs." (PMID 38758220, 2024).
Intraductal Papillary Mucinous Neoplasms (3 papers, 2022 to 2024). "However, pancreatic IPMNs have extensive mucin production; hence, there may also be a possible correlation between serum MUC16 levels and the biological behaviour of IPMNs." (PMID 36155113, 2022). "The analysis using histological subtypes of QCMG-PAAD cohort (n = 96) pointed to significant overexpression of MUC16 in de novo adenocarcinomas (n = 70) and adenosquamous (n = 7) cancers compared to PDAC-originated from Intraductal Papillary Mucinous Neoplasms (IPMNs) (n = 12)." (PMID 36816942, 2023).
intrahepatic cholangiocarcinoma (3 papers, 2021 to 2023). A carcinoma that arises from the intrahepatic bile duct epithelium in any site of the intrahepatic biliary tree. "MUC16 overexpression has also been linked to worse prognosis in intrahepatic cholangiocarcinoma and pancreatic tumors." (PMID 34327857, 2021).
keratoconjunctivitis (3 papers, 2016 to 2024). Inflammation of both the cornea and the conjunctiva. "Whereas mucin-16 (MUC16) has been implicated in keratoconjunctivitis, crystallins have been implicated in micro- and macro-glial activation and neuroinflammation." (PMID 39335566, 2024). "Here, we report that the highly virulent keratoconjunctivitis-causing HAdV-D37 induces release of the extracellular domain (ectodomain) of MUC16, a major component of the mucosal barrier of ocular surface epithelial cells, prior to infecting underlying cells." (PMID 27303700, 2016).
meningioma (3 papers, 2022 to 2024). A generally slow growing tumor attached to the dura mater. "Carcinoma transmembrane mucins such as MUC16 have high affinity for mesothelin expressed in the leptomeninges and meningiomas." (PMID 36497364, 2022). "Because a number of adenocarcinomas express MUC16, and adenocarcinomas represent one of the most common carcinomas metastasizing to the leptomeninges, it is conceivable that their interaction with meningioma mesothelin also facilitates anchoring there." (PMID 36497364, 2022). "Because a number of adenocarcinomas express MUC16, and adenocarcinomas represent one of the most common carcinomas metastasizing to the leptomeninges, it is conceivable that an interaction with meningioma mesothelin and mucins facilitates anchoring by adenocarcinoma metastasis to meningiomas." (PMID 36497364, 2022).
multiple myeloma (3 papers, 2021 to 2025). "Future studies are needed to investigate the role of MUC16 in myeloma biology." (PMID 38443358, 2024).
pancreatitis (3 papers, 2011 to 2024). Inflammation of the pancreas. "MUC16 mRNA levels were also measured by RT-PCR in the normal human pancreatic, pancreatitis, and PC tissues." (PMID 22066010, 2011). "The differential expression of MUC16 in PC was also examined by checking the expression of MUC16 at the transcriptional level by isolating mRNA from normal human pancreatic, pancreatitis and PC tissues." (PMID 22066010, 2011). "In some cases, patients that were low in total CA 19-9 were distinguishable from pancreatitis patients by their CA19-9 level on MUC16 or MUC5AC." (PMID 22220206, 2011). "Each of the proteins MUC1, MUC5AC, and MUC16 showed significantly higher levels in the cancer patients than in the pancreatitis patients, both for early and late stage cancers." (PMID 22220206, 2011). "MUC16 mRNA expression was absent in normal pancreatic tissues (0/2, 0%) but was present in 12/17 (71%) PC and 1/6 (16.7%) pancreatitis tissues." (PMID 22066010, 2011). "MUC16 is not expressed in the normal pancreatic ducts and is strongly upregulated in PC and detected in pancreatitis tissue." (PMID 22066010, 2011). "Interestingly, our results showed that the normal pancreas does not express MUC16 but its expression is significantly upregulated in 12/17 PC and 1/6 pancreatitis tissue." (PMID 22066010, 2011). "Thresholds could be set by which several cancer patients but no pancreatitis patients were elevated in either CA 19-9 on MUC5AC or CA 19-9 on MUC16 but not in total CA 19-9." (PMID 22220206, 2011). "In the non-NCT tumor specimens, varying levels of MUC16 expression were found in IPMN (N = 1; M = 2), PanIN (N = 2; M = 0.5), and pancreatitis (N = 1; M = 0) structures." (PMID 39456534, 2024).
serous carcinomas (3 papers, 2011 to 2023). "CA125/MUC16 mucin is a high-molecular-weight glycoprotein overexpressed in the majority of serous carcinomas, suggesting a possible role in the pathogenesis of these cancers." (PMID 21326240, 2011). "MUC16 (known as CA125), a well-established antibody, is a useful tool for classification of a variety of tumors, such as adenocarcinomas of the colon, breast carcinomas, malignant mesothelioma, uterine adenomatoid tumor, lung bronchoalveolar carcinoma, ovarian endometrioid and serous carcinomas." (PMID 37771441, 2023).
small cell lung carcinoma (3 papers, 2023 to 2026). Small cell lung cancer (SCLC) is a highly aggressive malignant neoplasm, accounting for 10-15% of lung cancer cases, characterized byrapid growth, and early metastasis. "Loss of CREBBP has been shown to reduce histone acetylation and transcription of cellular adhesion genes in small cell lung cancer, whereas MUC16, which is related to many types of cancers, increases metastasis via modulation of E‐cadherin, N‐cadherin, and vimentin expression." (PMID 38323355, 2024).
stomach cancer (3 papers, 2018 to 2024). "Specifically in GC, NPY1R is more highly expressed in the subgroup of gastric tumors presenting MUC16 mutations, and, in agreement with our results, the high expression of NPY1R was associated with dismal prognosis in the GC patients from the TCGA and ACRG cohorts." (PMID 38480611, 2024).
acute kidney injury (2 papers, 2021). Sudden and sustained deterioration of the kidney function characterized by decreased glomerular filtration rate, increased serum creatinine or oliguria. "Acute kidney injury was associated, and to a certain degree, predicted by IFNg, TWEAK, MMP7, and MUC-16." (PMID 34608231, 2021). "Of particular interest is the strong correlation between mortality, renal failure, and MUC1 mRNA expression and between mechanical ventilation and MUC4 and MUC16 mRNA expression." (PMID 34448730, 2021).
adenocarcinomas of the colon (2 papers, 2017 to 2023). "MUC16 is a very large transmembrane protein whose mutation rate is relatively high in colon adenocarcinoma (COAD) and colon mucinous adenocarcinoma (COMA) cancers, LUAD, bladder urothelial carcinoma (BLCA), PDAC, and UEC." (PMID 28978023, 2017).
adenoma (2 papers, 2023). A neoplasm arising from the epithelium. "The expression levels of Pax8, Cdh1 and Muc16 trended to be higher in both the sex cords and adenoma samples, as compared to the naïve and mature GC controls." (PMID 37174061, 2023). "In the adenoma group, GNAQ, KRAS, MUC16, and TTN were identified as the driver genes, whereas in the cancer group, only GNAQ and KRAS were identified as the driver genes." (PMID 37546388, 2023). "Additionally, Muc16 was statistically more highly expressed in adenomas compared to the mature GCs (p = 0.002) but was not different to that in sex cords (p = 0.117), even though average gene expression trended higher in the sex cords." (PMID 37174061, 2023).
Ascites (2 papers, 2019 to 2022). Accumulation of fluid in the peritoneal cavity (between the layers of the peritoneum that lines the abdomen). "The goal of this study was therefore to assess the effect of ascites on MUC16 expression in HPMCs." (PMID 31039761, 2019). "Although we identified a number of cytokines, chemokines and growth factors preferentially expressed in MUC16-stimulating ascites versus those without stimulating effects, we were unable to demonstrate that any of these factors were responsible for ascites-induced MUC16 expression in HPMCs." (PMID 31039761, 2019).
autoimmune disease (2 papers, 2009 to 2024). A disorder resulting from loss of function or tissue destruction of an organ or multiple organs, arising from humoral or cellular immune responses of the individual to their own tissue constituents. "However, a vaccine-based approach requires that immune tolerance to MUC16 is broken with associated risks of autoimmune disease." (PMID 38225646, 2024). "In addition, MUC16 protein is expressed on the surface epithelia of the cochlear duct and chief cells of the stomach, suggesting multiple physiologic roles for MUC16 and thus the potential for autoimmune disease upon induction of MUC16-specific antibodies." (PMID 38225646, 2024). "Interestingly, we showed that one of the neighbouring genes, mucin 16 (MUC16), of unknown function is expressed in several tissues that are relevant for psoriasis and/or other autoimmune diseases such as skin, thymus, and thyroid." (PMID 19525279, 2009).
breast tumor (2 papers, 2023 to 2024). "MUC16 is overexpressed in poorly differentiated breast tumors and overexpressed in the TNBC subtype as compared to other subtypes." (PMID 36918912, 2023).
cervical squamous cell carcinoma (2 papers, 2015 to 2024). A squamous cell carcinoma arising from the cervical epithelium. "It has been reported that the MUC family genes, MUC1, MUC16 and MUC4, are upregulated in cervical squamous cell carcinoma." (PMID 25789025, 2015).
endocervical adenocarcinoma (2 papers, 2015 to 2023). An adenocarcinoma that arises from the endocervix. "In contrast, a previous study demonstrated that overexpression of MUC16 was associated with lower survival rate in patients with endocervical adenocarcinoma." (PMID 26770020, 2015).
endometrioid carcinoma (2 papers, 2010 to 2021). "Consistent with previous reports of endometrioid carcinoma, FNAR cells display cell-surface expression of CA125 (MUC16, data not shown)." (PMID 20356397, 2010).
follicular lymphoma (2 papers, 2018 to 2021). Follicular lymphoma is a form of non-Hodgkin lymphoma characterized by a proliferation of B cells whose nodular structure of follicular architecture is preserved. "MUC16, also called carbohydrate antigen 125 (CA125, encoded by MUC16), is reportedly elevated in the serum of patients with NHL, including DLBCL, mucosa-associated lymphoid tissue lymphoma, follicular lymphoma." (PMID 30106962, 2018).
head and neck cancer (2 papers, 2017 to 2025). A primary or metastatic malignant neoplasm affecting the head and neck. "Given the role of epithelial cells in driving malignancy in the cancer types observed in this study, further investigation is warranted into the relationship between MUC16, skin reactions, and head and neck cancer." (PMID 40457720, 2025).
head and neck squamous cell carcinoma (2 papers, 2024 to 2025). A squamous cell carcinoma that arises from any of the following anatomic sites: lip and oral cavity, nasal cavity, paranasal sinuses, pharynx, larynx, and salivary glands. "MUC16 is a membrane-bound mucin expressed on epithelial surfaces, including the respiratory and reproductive tracts, and it is increasingly detected in head and neck squamous cell carcinomas." (PMID 40422614, 2025).
malignant mesothelioma (2 papers, 2022 to 2023). A malignant neoplasm of the pleura or peritoneum, arising from mesothelial cells. "The well-known interacting partner of mesothelin is CA125/MUC16, a member of the mucin family of glycoproteins which is expressed in ovarian cancer and malignant mesothelioma." (PMID 35326701, 2022).
metastatic cancer (2 papers, 2021 to 2023). A carcinoma which has spread from the original site of growth to another anatomic site. "Finally, the results concluded ch5E6 binding towards various endogenously generated surface-tethered forms of MUC16 in primary and metastatic cancer cell lines." (PMID 37567918, 2023). "According to our results, some highly frequently mutated genes may play an important role in the cell migration process, while other genes, such as MUC16, may influence the function of metastatic cancer cells in the other way, as its knockdown did not cause a significant change in cell migration." (PMID 34507604, 2021).